TMEM229A (transmembrane protein 229A)
Tractability: Antibody: UniProt predicts a signal peptide or a membrane-spanning region; the Human Protein Atlas places it where antibodies can reach.
Gene: Protein-coding gene on chromosome 7 (124,030,921 to 124,033,067, reverse strand). Ensembl gene ENSG00000234224.
Subcellular location: Membrane
Subcellular location (Human Protein Atlas): Plasma membrane
Gene Ontology:
Cellular component: membrane
Genetic constraint (gnomAD): Loss-of-function variants: 22 observed, 27.6 expected, observed/expected ratio (o/e) 0.8, 90% interval 0.57 to 1.14. The upper end of that interval is the gene's LOEUF score, 1.14, which puts it in group 4 of 6, group 1 being the genes least tolerant of losing a copy. Missense variants: 530 observed, 517.04 expected, observed/expected ratio (o/e) 1.03, 90% interval 0.95 to 1.1. Synonymous variants: 263 observed, 235.54 expected, observed/expected ratio (o/e) 1.12, 90% interval 1.01 to 1.24.
Homologues: Orthologues: chimpanzee TMEM229A (99% identical), macaque TMEM229A (97% identical), pig TMEM229A (85% identical), mouse Tmem229a (81% identical), rat Tmem229a (80% identical), guinea pig TMEM229A (60% identical), tropical clawed frog TMEM229A (50% identical). Paralogues in human: TMEM229B (12% identical).
Diseases named in the same sentence as TMEM229A in open-access papers:
TMEM229A is named in the same sentence as 11 diseases in open-access papers, as found by Europe PMC text mining. Sharing a sentence is not in itself a finding about the gene and the disease. The quoted sentences say what the papers report.
glioblastoma (2 papers, 2022 to 2023). The most malignant astrocytic tumor (WHO grade IV). "A growing number of studies revealed that TMEMs were differentially expressed among human cancers, including TMEM116 and TMEM229A in lung cancer, TMEM205 in hepatocellular carcinoma, TMEM168 in glioblastoma, and TMEM180 in colorectal cancer." (PMID 36313638, 2022).
glioma (1 paper, 2024). A benign or malignant brain and spinal cord tumor that arises from glial cells (astrocytes, oligodendrocytes, ependymal cells). "No data on the involvement of such genesas ASCC1, ZCCHC17 (participates in biogenesisof ribosomal DNA), PLAT, CISD1,TMEM229a and RANBP3L in the development and spread ofany glioma types have been found." (PMID 39539523, 2024).
lung adenocarcinoma (1 paper, 2024). A carcinoma that arises from the lung and is characterized by the presence of malignant glandular epithelial cells. "Association between TMEM229A Q200del mutation and clinicopathological features of patients with lung adenocarcinoma." (PMID 39188060, 2024).
cancer (3 papers, 2022 to 2026). A tumor composed of atypical neoplastic, often pleomorphic cells that invade other tissues. "Gene Expression Omnibus (GEO), The Cancer Genome Atlas (TCGA), and the European Genome-phenome Archive (EGA) have been utilized across multiple studies, suggesting that TMEMs such as TMEM213, TMEM245, and TMEM229A may be associated with lung cancer prognosis." (PMID 41596760, 2026).
tumor (1 paper, 2023). "The overexpression of TMEM229A reduces the expression of phosphorylatation levels of ERK, p-ERK, and ERK inhibitor (PD98059) partially suppresses this effect, indicating that the TMEM229A-inhibited tumor progression is partially mediated by inactivating the ERK signaling pathway in NSCLC." (PMID 37367036, 2023).
TMEM229A also shares sentences with these, for which no sentence is quoted: lung carcinoma (2 papers); Anxiety (1); breast carcinoma (1); colorectal cancer (1); hepatocellular carcinoma (1); Obesity (1).